MYC (MYC proto-oncogene, bHLH transcription factor)
Diseases named in the same sentence as MYC in open-access papers (continued):
Sharing a sentence is not in itself a finding about the gene and the disease.
tumor (continued). "Thus, expression of dominant-negative ΔF-FBXO28 was sufficient to suppress MYC-induced transformation in vitro and tumour growth in vivo." (PMID 23776131, 2013). "Deregulated MYC expression is a key event for malignant transformation by inducing multiple tumor-promoting events, including uncontrolled cell proliferation, cell mass expansion, and genomic instability, and contributes to the genesis of a large number of human cancers." (PMID 24459422, 2013). "MYC is a central oncogene that is required for carcinogenesis, as well as growth of metastatic lesions after the disseminated tumor cells have reached the target organ, and therefore, it is not surprising that it is a central regulator of earlier published signatures." (PMID 23113900, 2012). "Evidence from genetic analyses of human early liver lesions, primary and metastatic liver tumors, tumor-derived cell lines, and from different rodent models, unequivocally demonstrated that MYC deregulation is a critical alteration in the initiation and progression of HCC." (PMID 22580498, 2012). "Interestingly, recent studies have also demonstrated a major contribution of MYC to tumor angiogenesis." (PMID 22383169, 2012). "This may also explain differences in MYC-induced tumor types between different retroviral transduction systems." (PMID 22393362, 2012). "The pathologic effect of MYC has been ascribed to its ability to control multiplecellular processes such as cell growth, differentiation, apoptosis, DNA damage response, genomic instability, angiogenesis, and tumor invasiveness." (PMID 22539939, 2012). "Another possibility is that the tumor initiating MYC target cell(s) differ between the systems." (PMID 22393362, 2012). "TRUSS expression is reduced in tumor cells, suggesting that downregulation may promote tumor formation by enhancing MYC protein stability." (PMID 22754359, 2012). "Gene Set Enrichment Analysis (GSEA) of the primary DLBCLs with >50% MYC positive tumor nuclei correlates with upregulated MYC and MYC target genes, providing confirmation that the detection of a high MYC protein expression by IHC is associated with an activated MYC transcriptional profile." (PMID 22511926, 2012). "In resting cells, MYC activity is often minimal because of low mRNA and protein levels; in contrast, MYC activity is strongly induced in tumor cells by multiple mechanisms, including increased transcription, stabilization of the protein, gene amplification, and chromosomal translocation." (PMID 21573126, 2011). "Neuroradiological evaluation and c-MYC mRNA expression analysis was of sufficient quality to determine response rate on the residual tumor according to c-MYC mRNA expression following treatment by postoperative radiotherapy (19/21 patients) and by postoperative chemotherapy (43/45 patients)." (PMID 21324178, 2011). "Animal studies have shown that even a transient MYC downregulation appears to be sufficient for diminishing tumor tissue and that the tumor may actually regress upon MYC reactivation." (PMID 22132187, 2011).
tumor (continued). "Therefore, a gene such as MYC (most often over expressed in tumor cells) which has a mean sample expression value of 8.93 in the eight TCGA normal samples and a mean tumor sample expression value of 7.75 (from 339 tumor samples) is not observed by this method." (PMID 22174824, 2011). "However, we observed only a weak correlation between MYC and NDRG2 mRNA expression in normal and tumor samples from breast tissue, indicating that MYC and NDRG2 are co-regulated." (PMID 21226903, 2011). "Notably, MYC is a key regulator of miRNA transcription and negatively controls expression of various tumor-suppressive miRNA clusters including once again the let-7 family but in addition the miR-30, -26, -34 and -29 families." (PMID 21835047, 2011). "Future experiments may examine HCC development in MYC/Rb mutant mice in which p107 and or p130 are also inactivated, as well as the tumor phenotypes of mice in which Rb is deleted and MYC is activated in other tissues and organs." (PMID 21573126, 2011). "We hypothesized that activation of MYC in this context may facilitate and accelerate tumor development in the liver." (PMID 21573126, 2011). "We analyzed whether c-MYC expression, determined in the primary MB tumors, has an effect - as determined by neuroradiological evaluation - on the response of residual tumor to postoperative IR and postoperative chemotherapy." (PMID 21324178, 2011). "In order to investigate whether our observations might be of clinical relevance, we analyzed whether the response of postoperative residual tumor to radio- and chemotherapy depends on the c-MYC mRNA expression in MB patients." (PMID 21324178, 2011). "High levels of c-MYC have been clearly shown to have a tumour-promoting effect." (PMID 20930934, 2010). "MYC is an oncogenic transcription factor overexpressed in a variety of tumor types." (PMID 20195545, 2010). "SP1 cooperates with other prominent transcription factors including oncogenes such as MYC, which may contribute to tumor cell proliferation and growth." (PMID 20576088, 2010). "MYC is one of the most frequently de-regulated oncogenes in cancer and, in the absence of both enzymes, may become activated and accelerate tumor growth." (PMID 20441585, 2010). "Indeed, all human tumor groups showed a recurrent gain on chromosome 8q, likewise all mouse tumor groups showed a recurrent gain on its syntenic region, on chromosome 15, centering exactly on the MYC oncogene." (PMID 20735817, 2010). "The ability of c-MYC to induce angiogenesis has been observed previously in other tumor models." (PMID 19551151, 2009). "Moreover c-MYC induces production of VEGF by tumor cells leading to tumor vascularisation with unusual vessels that are mosaics containing PECAM-1 positive and PGP 9.5 positive endothelial cells." (PMID 19551151, 2009). "Following in vivo validation, targeting c-MYC might represent a promising strategy to reduce tumor growth in pretreated MB patients whose tumors have ceased to respond to chemotherapy." (PMID 19134217, 2009). "C-RAF cooperates with c-MYC in tumor progression by suppressing apoptosis." (PMID 19551151, 2009). "In addition to promoting an immature phenotype of tumor cells c-MYC accelerates growth of primary tumors by induction of angiogenesis." (PMID 19551151, 2009). "Combining c-MYC and C-RAF transgenes caused appearance of a phenotypic switch from cuboidal to alveolar papillary/columnar epithelial cells (APECs) that are the most rapidly growing tumor cells and also predominate in liver metastasis." (PMID 19551151, 2009). "MYC overexpression influences cell cycle checkpoints, allowing some tumor cells to survive drug treatment and favoring the selection of a subpopulation with increased genomic instability and drug resistance or with a more aggressive tumor phenotype." (PMID 19421315, 2009). "However one out of the five cases of K-Ras positive c-MYC tumor derived metastasis was positive for mutant K-Ras." (PMID 19551151, 2009).
tumor (continued). "The apparent under-expression of MYC upon amplification relative to whole ovary normal samples could be due to different cell type proportions in the tumor and normal samples." (PMID 19419571, 2009). "In a random series of 110 HCC patients, the mRNA of HIF-1alpha, inflammation related factors (COX-2, MMP7 and MMP9), angiogenesis related factors (VEGF and PDGFRA) and MYC in tumor tissue were detected by real-time RT-PCR and HIF-1alpha protein was assessed by immunohistochemistry." (PMID 19948069, 2009). "Our investigation shows that c-MYC inhibition reduces tumor cell growth suggesting that c-MYC might be an attractive target in MB to inhibit tumor growth." (PMID 19134217, 2009). "As many cancer-related genes have been linked to the development of polyploidy, for example MYC, APC, Pim-1, BRCA2, and Aurora-A, our model may reflect an actual pathway for tumor initiation." (PMID 18596907, 2008). "This raises the possibility that MAX may also be limiting in tumours where c-MYC levels are very high." (PMID 18493233, 2008). "The expression of MYC is further increased in tumor cells by an additional 10-fold through an unknown mechanism." (PMID 18628958, 2008). "Similarly, we found HEL protein in tumors that arose following transplantation of cells from a primary Eμ-MYC/BCRHEL/sHEL tumor." (PMID 18578569, 2008). "Although the chimeric transcripts might contribute to tumor formation, an oncogenic effect could also be mediated by the MYC protooncogene, just 40 to 60 kb upstream." (PMID 18194563, 2008). "However, to date it has not been directly examined if the coordinate inactivation of both MYC and mutant Ras would be more effective in inducing sustained tumor regression." (PMID 18461184, 2008). "It has also been recently reported, during the 2005 San Antonio meeting, that MYC status could be a predictive parameter of tumour response to anti-HER2 therapy." (PMID 17262082, 2007). "Cell lines derived from Myc-induced neoplasms of this sort may provide a good model system for the design and testing of new approaches to prevent and treat MYC-driven B cell and plasma cell neoplasms in human beings." (PMID 16759389, 2006). "Hence, MYC overexpression appears to induce cellular proliferation in neonatal hepatocytes that progresses rapidly to neoplasia." (PMID 15455033, 2004). "Mice in which MYC was activated at birth (neonates) succumbed to neoplasia within 8 weeks." (PMID 15455033, 2004). "Collectively, our findings elucidate a mechanism by which a tumor-specific trans-acting lncRNA modulates oncogenic MYC expression through long-range chromatin interactions, suggesting IGF1R-AS1 may play an important role in the pathogenesis of MYC-driven malignancies." (PMID 41857039, 2026). "In addition, the analysis of PCa tissue samples revealed that elevated HNF1A expression was significantly correlated with higher pathological Gleason scores, larger tumor sizes, and tumor metastasis, as well as enrichment of pathways related to MYC and E2F targets." (PMID 41583511, 2026). "Disruption of this feedback loop may effectively inhibit the role of MYC in tumor resistance." (PMID 39990228, 2025). "These strategies aim to either reduce MYC transcription, translation, or stability; target MYC’s interactions with its binding partners; block MYC’s access to downstream genes; or exploit the vulnerabilities of MYC-dependent tumor cells through efficient synthetic lethality combinations." (PMID 40126351, 2025). "Besides such prophylaxis, partial inhibition of MYC activity in an adjuvant setting might help to attenuate tumor recurrence or could enhance the efficacy of combination chemotherapy." (PMID 40970130, 2025). "Additional work is needed to determine whether SCLC-P tumor subtypes, which express the highest levels of MYC across all SCLC subtypes, would benefit from KBTBD4 activation through UM171, which not only degrades CoREST complex proteins but also suppresses MYC expression." (PMID 40479062, 2025).
tumor (continued). "Recent studies have shown that I3C-mediated inhibition of WWP1 can restore PTEN stability and suppress tumor progression in MYC-driven cancer models, implying how therapeutic targeting of the WWP1-PTEN axis could be effective against a broad spectrum of cancers driven by the MYC oncogene." (PMID 40002221, 2025). "Additionally, MYC can affect the tumor immune microenvironment through multiple pathways." (PMID 39897587, 2025). "Two primary and three MYC-amplified cell lines localized at the cerebellum and disseminated at leptomeninges have been treated with Hu5F9-G4 antibody (also named Magrolimab) intraperitoneally, and a reduction of tumor burden and increase of OS in mice have been detected." (PMID 40677711, 2025). "Tumour haemorrhage did not correlate significantly with mutational burden but occurred predominantly in cohorts with a mutational pattern showing activated Ctnnb1 and Pten loss without MYC overexpression." (PMID 39972137, 2025). "Here we show that monotherapy with selective PRMT5 inhibitors induced a potent anti-tumor activity across several cellular and animal models of ACC, which was paralleled by downregulation of genes associated with ACC tumorigenesis, including MYB and MYC (the recognized drivers of ACC progression)." (PMID 39794830, 2025). "Furthermore, when compared to the oe-NCL + oe-MYC + oe-NC group, the oe-NCL + oe-MYC + oe-TXNIP group exhibited enhanced tumor cell proliferation, reduced apoptosis, significantly decreased permeability, and a notable increase in the invasive spread capacity of spheroids." (PMID 40346484, 2025). "Furthermore, integration of mutational profiles and CNV data suggests that horizontal targeting of RAS/PI3K pathways and MYC may be an effective strategy for this tumor type." (PMID 40500270, 2025). "MYC is a well-known transcriptional regulator of a multitude of cellular programs, including cell cycle regulation, survival, cell fate decisions, ribosome biogenesis and translation, thus having a tumor-promoting role in cooperation with other oncogenic events in the vast majority of cancers." (PMID 40241199, 2025). "In turn, MYC is known to regulate genes involved in cell cycle progression and may influence immunosuppressive molecules and cytokines, which could contribute to tumor growth and immune evasion." (PMID 40246846, 2025). "In addition, MYC directly suppresses STING/IFN signaling in tumor cells with genomic instability." (PMID 40584290, 2025). "However, as VTE is a thrombosis - related disorder with different pathological processes from tumors, the specific function of MYC in thrombosis may differ from its role in tumor immune escape." (PMID 41210882, 2025). "Indeed, some studies have suggested that abnormally high levels of MYC may promote resistance to immunotherapy, particularly by inhibiting the extrinsic immune response against tumor cells." (PMID 39897587, 2025). "The role of MYC in tumors manifests in several aspects, including promoting cell proliferation, metabolic reprogramming, inhibiting apoptosis, promoting genomic instability, modulating the tumor microenvironment and cross-regulating with other signaling pathways." (PMID 40303931, 2025). "We hypothesize that inhibition of key miRNAs within the miR-17/92 cluster (miR-17, miR-19a, and miR-20a) using sponge constructs will destabilize the MYC dosage compensation system, unleash cytotoxicity and reduce tumor cell viability depending on MYC expression levels." (PMID 40940795, 2025). "Additionally, LSD1 inhibitors have been reported to suppress MYC signaling and reduce tumor growth." (PMID 40428124, 2025).
tumor (continued). "These intrinsic events within tumor cells enhance ER stress‐associated ubiquitylation and degradation by triggering ubiquitin via the E1 activase UBA6, facilitating ubiquitin transferring to E2 conjugate UBE2Z and increasing the activities of E3 ligase FBXW7 to degrade both EZH2 and MYC." (PMID 39823459, 2025). "Therefore, targeting MYC and taurine supplementation may enhance the tumor-killing capacity of immune cells." (PMID 40732268, 2025). "Specifically, the upregulation of MYC targets suggests a higher rate of cancer cell growth and metabolism, while the activation of the G2M checkpoint pathway points to accelerated cell cycle progression, potentially leading to rapid tumor development and progression." (PMID 40026531, 2025). "Also, MYC is one of such major oncogenes responsible for tumor progression in PDAC." (PMID 40216980, 2025). "Consequently, these data suggest that a dual inhibition strategy in which both AZIN1 and polyamine endocytosis are targeted simultaneously might be a novel approach to be considered in MYC amplified tumor subgroups." (PMID 39962590, 2025). "Thus, universal therapeutic schemes to thwart pathological regulation of MYC expression may prove elusive and such strategies may need to be individually tailored to intercept tumor-specific MYC-upregulating pathways." (PMID 40970130, 2025). "The significant enrichment in MYC target genes and the high expression of cancer stemness genes that we observed in CTCs with a platelet gene signature suggest the pro-oncogenic nature of this interaction, in agreement with the findings of studies in other tumor types." (PMID 40003901, 2025). "Thus, we measured the expression level of MYC in these tumour grafts." (PMID 40186514, 2025). "Moreover, SLC25A32 promotes tumor progression through MYC-mediated pathways." (PMID 41465541, 2025). "Moreover, hypusinated eIF5A promotes tumor growth by up-regulating MYC elongation." (PMID 40040695, 2025). "However, in approximately 70% of cancer cases, MYC is dysregulated, which is characterized by markedly elevated expression levels and excessive activation of its transcriptional function, enabling tumor cells to proliferate uncontrollably and potentially metastasize to nonprimary tissues." (PMID 40732268, 2025). "To verify whether monocyte- and macrophage-CM modulate the tumor plasticity of SCC cells, we analyzed the expression of genes associated with epithelial-mesenchymal transition (EPCAM, SOX2), stemness (NANOG, MYC, EZH2), and neuroendocrine differentiation (CHGA, AURKA, MYCN)." (PMID 41259557, 2025). "The IMS functional annotations showed high enrichment of ncRNA metabolism, tRNA modification, MYC variants, and RNA Polymerase I and III, which may point to potential tumor adaptations that enable resistance against conventional therapies and thereby also warrants further research." (PMID 40269124, 2025). "Furthermore, there is emerging evidence of the co-expression of TIMP1 with both CXCL8 and c-MYC, which may influence PD-L1 expression and thus, the immune escape mechanisms of tumor cells." (PMID 40290432, 2025). "In addition to directly regulating the expression of CD47, MYC may further help tumor cells escape phagocytosis by regulating the expression of argininosuccinate synthetase 1 (ASS1), a key enzyme in arginine biosynthesis." (PMID 40732268, 2025).